TNC (tenascin C)
Diseases named in the same sentence as TNC in open-access papers (continued):
Sharing a sentence is not in itself a finding about the gene and the disease.
inflammatory bowel disease (6 papers, 2019 to 2025). A spectrum of small and large bowel inflammatory diseases of unknown etiology. "In inflammatory bowel disease, TNC expression is significantly increased in both intestinal mucosa and serum, correlating with histological inflammation and immune cell infiltration." (PMID 40564778, 2025). "In an earlier study, the transcriptional level of tenascin-c was found increased in ulcerated areas during inflammatory bowel disease (IBD) in the murine model of IBD." (PMID 39292008, 2024). "Our imaging data suggest the alternatively spliced D domain of tenascin C is a promising target for delivery-based applications in inflammatory bowel diseases." (PMID 35906512, 2023).
oral cancer (6 papers, 2011 to 2024). "TNC was identified to be the most frequent mutated gene among the 17 IRGPs in oral cancer." (PMID 35804390, 2022). "The top 3 IRGPs most strongly and positively correlated with the outcome of oral cancer were TNFRSF12A|TNC, PLAU|DEFB1, and TAP|IGHG2." (PMID 35804390, 2022). "Furthermore, the protein levels of TNC in the stroma have been proven to be an excellent prognostic marker in oral cancer patients, suggesting that five-year survival rate was 88% when stromal TNC was negative; however, for cases with overexpression of TNC, it decreased to 43%." (PMID 34326893, 2021). "On literature search for proteomic profiling of POSTN, TNC, CAV1 and FSCN1 in OSCC or oral cancer, we could not find any related studies reported till date." (PMID 33739025, 2021).
osteoarthritis (6 papers, 2009 to 2025). A noninflammatory degenerative joint disease occurring chiefly in older persons, characterized by degeneration of the articular cartilage, hypertrophy of bone at the margins and changes in the synovial membrane. "In particular, centromere protein-C, insulin growth factor binding protein 2, and LDH have not been previously linked to an imbalance of damage and repair in osteoarthritis, whereas, TNC and COL2A1 have already been reported." (PMID 23773399, 2013). "While statistical significance was not confirmed by RT-qPCR (p = 0.0665), upregulation of TNC has been noted in early stages of osteoarthritis and also during the repair process of many other tissues through in situ hybridization, immunohistochemistry, and knockout mouse studies." (PMID 19751507, 2009).
renal fibrosis (6 papers, 2019 to 2026). A final common manifestation of a wide variety of chronic kidney diseases characterized by glomerulosclerosis and tubulointerstitial fibrosis. "Blockade of these pathways reversed the EMT and alleviated renal fibrosis, suggesting that the TNC/integrin αvβ6/FAK signaling cascade plays an important role in renal fibrosis." (PMID 40981103, 2025). "Further investigation of the key markers of renal fibrosis showed a reduced induction of both tenascin-C and αSMA in Ybx3 knockouts, as well as collagen I and III." (PMID 37408260, 2023). "The knockdown of TNC in vivo inhibited fibroblast activation and proliferation, which in turn reduced renal fibrosis." (PMID 36932062, 2023). "Consistently, either knockdown of TNC or knockout of TLR4 in vivo blocks the activation of TLR4/NF‐κB signaling and represses renal inflammation, alleviates renal fibrosis, and preserves renal function." (PMID 41042124, 2026).
scleroderma (6 papers, 2016 to 2025). Scleroderma is a rare autoimmune connective tissue disorder characterized by abnormal hardening of the skin and, sometimes, other organs. "Another study investigated the pathogenic role of endogenous toll-like receptor (TLR) activators and tenascin-C association in fibroblasts of patients with scleroderma and mouse models of organ fibrosis." (PMID 39114190, 2024). "There were elevated expression levels of tenascin-C in scleroderma fibroblasts and fibrotic skin tissues from mice." (PMID 39114190, 2024). "The aggregation of Tenascin C (TNC) is widely recognized as a significant contributor to collagen deposition in the development of scleroderma." (PMID 39072324, 2024). "FTO/TNC may become a new target for the treatment of Scleroderma in the future." (PMID 39072324, 2024). "Moreover, collagen and tenascin-C deposition in the hypodermis and αSMA accumulation were reduced, indicating for the first time that tenascin-C plays a role in the development of hypodermal fibrosis in the Tsk/+ mouse model of scleroderma." (PMID 27256716, 2016). "In conclusion, previous studies reported an increase in serum tenascin-C levels in chronic autoimmune diseases, including RA, SLE, and scleroderma, yet tenascin-C levels do not increase in the autoinflammatory FMF disease." (PMID 39114190, 2024). "Despite reports of elevated tenascin-C levels in rheumatologic diseases like RA, ankylosing spondylitis (AS), and scleroderma, as well as in other chronic diseases, no prior research has examined its role in autoinflammatory diseases." (PMID 39114190, 2024). "Additionally, a variety of other genes associated with inflammatory as well as malignant diseases were enriched in scleroderma fibroblasts (POSTN, PRSS23, TNC, and SERPINE2)." (PMID 37443817, 2023). "Studies using scleroderma cells revealed that treatment with TGF‐β1, in combination with antibodies BB7 and a pan‐TGF‐β blocking antibody, or in the presence of an ALK5 inhibitor for 48 hours, resulted in a reduction of Col‐1, TNC, CCN2, and αSMA to levels comparable with control cells." (PMID 39800950, 2025).
bronchopulmonary dysplasia (5 papers, 2011 to 2024). Bronchopulmonary dysplasia is a chronic respiratory disease that results from complications related to lung injury during the treatment of infant acute respiratory distress syndrome in low-birth-weight premature infants or from abnormal lung development in older infants. "TNC is highly expressed in such chronic lung diseases as COPD, bronchopulmonary dysplasia (BPD), respiratory distress syndrome (RDS), IPF or asthma." (PMID 34777012, 2021).
cardiomyopathies (5 papers, 2012 to 2025). "Since we did not observe any changes in cell death, fibrosis or inflammation, we propose a new paradigm that smartly formulating TnC may be a viable therapeutic approach for many cardiomyopathies." (PMID 26908229, 2016). "Thus, an aberrant rate of Ca2+ dissociation from TnC could potentially contribute to the diastolic dysfunction typically observed with the various cardiomyopathies." (PMID 22675533, 2012).
cervical cancer (5 papers, 2015 to 2024). A primary or metastatic malignant neoplasm involving the cervix. "Synthesized SPION-anti-tenascin-C, a magnetic probe oriented specifically to tenascin-C, possessed the non-invasive ability to capture specific MLNs with high expression of tenascin-C in preoperative cervical cancer patients." (PMID 37735449, 2023). "This study aimed to establish a machine learning model that combines radiomics based on PET imaging with tenascin-C (TNC) and cyclooxygenase-2 (COX-2) for predicting lymphovascular space invasion (LVSI) in patients with early-stage cervical cancer." (PMID 34320931, 2021). "High levels of tenascin-C could be observed in cervical cancer tissues with node metastasis but not in non-metastatic patients and normal cervix tissues." (PMID 37735449, 2023).
chondrosarcoma (5 papers, 2012 to 2024). A malignant cartilaginous matrix-producing mesenchymal neoplasm arising from the bone and soft tissue. "This notion is further supported by the crucial role of TNC, highly expressed in the tumor stroma, in promoting chondrosarcoma cell survival via TNC-mediated adhesion and Akt activation." (PMID 38542153, 2024). "In TNXB family, TNC was reported to inhibit human chondrosarcoma cell apoptosis by activation of AKT." (PMID 38819423, 2024). "However, TNC was reported to induce MMP-1 expression via MEK1 activation in chondrosarcoma cells and activate ERK, JNK, and p38 MAPK, and integrin β1 and β3 in airway smooth muscle cells." (PMID 33217999, 2020). "All three are in the “multifunctional” signature of dedifferentiated chondrosarcoma lung metastases—MMP1 and CXCL1 were significantly differentially expressed in 4 out of 5 metastases; TNC was differentially expressed in all 5 metastases and it is also a component of the “biased” signature)." (PMID 22448124, 2012).
depression (5 papers, 2015 to 2025). "Tenascin-C plays a key role in the development of the hippocampal region, which has been connected to depression." (PMID 39838666, 2025). "Serum levels of testosterone, estradiol, and depression risk biomarkers (thyroid hormone, lipids, hs-CRP, Tenascin-C [TNC], GDF15, KLF4, Gas6, and sgp130) were measured." (PMID 36635686, 2023). "Out of our 26-analyte panel, only three proteins (ApoH, ApoA1 and B2M) were altered in bipolar disorder patients and four (MIF, ACE, TNC and ILra) were changed in patients with depression." (PMID 26171982, 2015). "Combining our findings investigated from human samples and in vivo mouse models, Tes and TNC might exert regulatory influences on both OP and major depressive disorder." (PMID 40444453, 2025). "Furthermore, proteomic studies have reported tenascin-C as a suggested biomarker for major depressive disorder (MDD)." (PMID 39838666, 2025).
Ewing sarcoma (5 papers, 2016 to 2020). A small round cell tumor that lacks morphologic, immunohistochemical, and electron microscopic evidence of neuroectodermal differentiation. "Poor prognostic features were found in two other patients: low expression of PAX8, FHIT, CASP10, CHD2, with high expression of CHD11, FUS, and MTA1 in a patient with Ewing sarcoma, and gain of 1q and loss of 6q and overexpression of TNC, CALB1, PLAG1, ALDH1L1, and RELN in a patient with ependymoma." (PMID 28007021, 2016). "This gene group includes MCAM and TNC, both recently established metastasis-promoting factors in Ewing sarcoma." (PMID 33196691, 2020). "TNC is abundantly expressed in most Ewing sarcomas, and high expression levels correlate with adverse outcomes." (PMID 32326412, 2020). "High level of tenascin C contributes to the Ewing sarcoma metastatic phenotype, modulating tumor microenvironment." (PMID 31370265, 2019). "Similarly, we observed the same regulatory effects on another recently demonstrated pro-metastatic gene in Ewing sarcoma, TNC." (PMID 33196691, 2020). "However, in Ewing sarcoma, Wnt/β-catenin activation-induced expression of tenascin C, a secreted extracellular matrix protein that plays a key role during metastasis establishment in different types of cancer." (PMID 31370265, 2019).
metastatic disease (5 papers, 2012 to 2025). "In CAFs from metastatic tumors, a decrease in CCL2, MMP-2, TNC, OPN, and TGFβ levels and an increase in only TIMP1, PDPN, and SPP1 mRNA levels (without an effect on protein levels) was observed after calcitriol treatment." (PMID 38360633, 2024). "While TNC expression in the primary tumors also correlates with distant metastatic disease, this trend is not statistically significant." (PMID 39951495, 2025). "Chemokine CCL21 can induce the migration of antigen-presenting dendritic cells from the interstitium to the lymphatic system, and another study indicated that tenascin-C enhanced an immunosuppressive lymphoid stroma through CCL21/CCR7 signaling, leading to an increase in metastatic tumors." (PMID 34177903, 2021).
type II diabetes (5 papers, 2020 to 2025). "Elevated serum tenascin-C (TNC) levels were shown to be indicators of increased risk of cardiovascular events and death from type II diabetes, but the role of TNX in these processes must be further elucidated." (PMID 37189830, 2023). "In a rat model of a rotator cuff tendon associated with persistent type II diabetes, tendons were characterized by the increased expression of tenascin C (TNC) and fatty acid binding protein 4 (FABP4), overall contributing to a significant biomechanical decline of the rotator cuff tendon." (PMID 40001567, 2025).
Alzheimer disease (4 papers, 2017 to 2021). A progressive, neurodegenerative disease characterized by loss of function and death of nerve cells in several areas of the brain leading to loss of cognitive function such as memory and language. "The beneficial effect of TnC on Alzheimer’s disease pathogenesis implicates this ECM glycoprotein as a new therapeutic target." (PMID 33996833, 2021). "TnC has been recognized as another molecule involved in chronic inflammation in Alzheimer’s disease since its gene transcription is significantly increased in both cultured microglia after amyloid β (Aβ) peptide challenge, as well as in the brain of Alzheimer’s disease mouse model." (PMID 33996833, 2021). "Interestingly, in patients with Alzheimer’s disease (AD), TNC is co-expressed in Aβ plaques." (PMID 28824389, 2017).
Aortic dissection (4 papers, 2020 to 2024). Aortic dissection refers to a tear in the intimal layer of the aorta causing a separation between the intima and the medial layers of the aorta. "Elevated serum Tenascin-C levels were associated with a higher probability of death in patients with acute aortic dissection." (PMID 34456984, 2021). "Upcoming diagnostictests for aortic dissection are related to vascular damage include calponin,plasma matrix metalloproteinase 8 and tenascin-C and may enter clinicalroutine diagnostic in the near future." (PMID 39076909, 2022). "The objective of this article is to evaluate whether Tenascin-C assays could be of use for predicting prognosis in abdominal aortic aneurysms and acute aortic dissection." (PMID 34456984, 2021). "In the recent study, a combination of tenascin-C and D-dimer or CRP can improve the performance of predicting in-hospital death from acute aortic dissection." (PMID 32034642, 2020).
colitis (4 papers, 2019 to 2023). Inflammation of the colon. "Having shown a protective effect of loss of tenascin-C during the acute phase of the DSS model the observation period was extended to study the impact of tenascin-C on colitis resolution." (PMID 35669358, 2022). "Furthermore, the membrane bound extracellular protease MMP14 has been implicated in the pathogenesis of IBD and thus with tenascin-C’s known link to its expression shows another potential mechanism by which tenascin-C deficiency may be protective in colitis." (PMID 35669358, 2022). "The increased expression is in line with previously reported omic studies of DSS colitis, which have also reported tenascin-C upregulation in the colitic colon by immunohistochemistry, gene expression microarray and mass spectrometry." (PMID 35669358, 2022). "To assess the impact of tenascin-C on the development of experimental colitis we next studied the colon architecture of DSS treated Tnc−/− mice." (PMID 35669358, 2022). "Together these observations imply that tenascin-C’s upregulation in colitis is conserved across disease models and types as well as species, implicating it in a common colitis promoting role." (PMID 35669358, 2022). "In contrast, a previous report proposed tenascin-C as a protective factor in DSS colitis which mediated epithelial healing." (PMID 35669358, 2022). "To study tenascin-C’s role in colitis pathology we investigated its expression in a murine model of IBD." (PMID 35669358, 2022). "In terms of colitis induced tenascin-C staining this appeared to predominantly occur in these damaged ulcerated areas." (PMID 35669358, 2022). "Therefore, to advance previous RNA expression studies we have in this study used the dextran sodium sulphate (DSS) colitis model to examine the spatiotemporal expression of tenascin-C during the development of murine colitis." (PMID 35669358, 2022). "•Tenascin-C knock-out mice were partly protected from DSS induced colitis." (PMID 35669358, 2022). "For example, in a commonly used murine colitis model, the addition of dextran sulfate sodium (DSS) to drinking water resulted in tenascin C upregulation in damaged mucosal areas." (PMID 35906512, 2023). "In this study, the distribution of tenascin-C within the colon was altered and its expression levels were increased in DSS induced experimental colitis." (PMID 35669358, 2022). "The mechanisms by which tenascin-C expression is induced may involve the microbiome, which has been shown to be essential for the establishment of DSS colitis." (PMID 35669358, 2022). "In addition to sequence alignment showing strong species conservation for TNC D across models, our IHC pointed to unique expression in the lamina propria in clinical IBD colon biopsies and in colonic lesions of the commonly used DSS mouse colitis model." (PMID 35906512, 2023). "Furthermore, to determine any contribution of tenascin-C in driving the inflammation seen in this model we utilized a tenascin-C knockout (Tnc−/−) mouse, which in combination with the DSS model allowed the dissection of tenascin-Cs contribution to pathological changes in colitis." (PMID 35669358, 2022). "Finally, tenascin-C expression also trended to increase in DSS treated mice, whereas this was not the case in VP treated mice, suggesting that tissue stiffening could also occurred through YAP during colitis." (PMID 34956224, 2021). "Additionally, tenascin-C protein has also been shown to be elevated in the colitic colons of Il-10−/− mice, a genetic model of IBD, suggesting this upregulation is not specific to the DSS colitis model." (PMID 35669358, 2022).
coronary artery disease (4 papers, 2021 to 2025). "Other researchers have found correlations between TnC levels and the Gensini Score—an angiographic scoring system—and have suggested that the concentration of TnC in the serum may be helpful in the risk assessment for coronary artery disease, prior to conducting angiography." (PMID 41010873, 2025). "In a few studies, higher TnC serum levels were observed in patients with coronary artery disease, as opposed to patients in the control group." (PMID 41010873, 2025).
Crohn disease (4 papers, 2013 to 2025). A gastrointestinal disorder characterized by chronic inflammation involving all layers of the intestinal wall, noncaseating granulomas affecting the intestinal wall and regional lymph nodes, and transmural fibrosis. "This systemic increase in IBD is also reflected at the local level with a number of histological studies reporting high levels of tenascin-C staining in the inflamed gut tissue of patients with ulcerative colitis, Crohn’s disease, and microscopic colitis." (PMID 35669358, 2022). "Tenascin C has recently been found to be cleaved by meprin β and possibly to be involved in Crohn’s disease." (PMID 22940918, 2013). "Likewise, the altered distribution of tenascin-C noted in this study matches the disorganised tenascin-C deposition within the lamina propria of samples from patients with either ulcerative colitis or Crohn’s disease." (PMID 35669358, 2022). "TNC is an extracellular-matrix (ECM) glycoprotein that is highly expressed during embryogenesis and re-appears in response to tissue injury, during wound healing, and with Crohn’s disease and ulcerative colitis." (PMID 35140270, 2022).